CENPW (centromere protein W)
Diseases named in the same sentence as CENPW in open-access papers:
CENPW is named in the same sentence as 47 diseases in open-access papers, as found by Europe PMC text mining. Sharing a sentence is not in itself a finding about the gene and the disease. The quoted sentences say what the papers report.
breast carcinoma (4 papers, 2020 to 2024). "In this study, we verified that CENPW expression is up-regulated in breast carcinoma and positively associated with the level of immune cell infiltration." (PMID 35783290, 2022). "The co-expression profile showed that CENPW had the highest association coefficient with CDCA7 among 129 breast carcinoma samples in the LU Breast dataset." (PMID 35783290, 2022). "We discovered that CENPW, which is highly expressed in breast carcinoma, is associated with a poor prognosis of breast carcinoma." (PMID 35783290, 2022). "In summary, these data showed that CENPW expression is associated with poor prognosis in breast cancer." (PMID 35783290, 2022). "It was found that in 6,801 breast cancer patients, 2% had mutations in the CENPW gene, and alterations with amplification were more common." (PMID 35783290, 2022). "The CENPW expression was positively linked to the transcription level of CDCA7 in a 50-gene qPCR assay (PAM50) for breast carcinoma subtypes." (PMID 35783290, 2022). "To further understand the influence of CENPW gene mutations on breast carcinoma patients, we used the cBioPortal database and detected mutations in seven breast cancer databases." (PMID 35783290, 2022). "Differences in mRNA expression of CENPW in breast carcinoma were also confirmed using the UALCAN database." (PMID 35783290, 2022). "To explore the role of CENPW in breast cancer cells, we transfected MDA-MB-231 and BT-549 cells with two specific siRNA sequences to induce knockdown of CENPW expression." (PMID 35783290, 2022). "This study presents evidence that high CENPW expression in breast cancer generates poor prognosis and can therefore be used as a novel biomarker for breast carcinoma." (PMID 35783290, 2022). "According to the Richardson Breast two dataset, the CENPW expression in ductal breast cancer was distinctly higher than that in normal tissues." (PMID 35783290, 2022). "In the current study, several databases were used to evaluate the role of CENPW in breast carcinoma." (PMID 35783290, 2022). "Our subsequent studies verified that knockdown of CENPW significantly inhibits the proliferation and migration of breast carcinoma cells and promotes their apoptosis rate." (PMID 35783290, 2022). "Our results provide bioinformatics data and experimental evidence that CENPW can be used as a unique biomarker for breast carcinoma, and as a hopeful therapeutic option for the development of related inhibitors to treat breast cancer at the genetic level." (PMID 35783290, 2022). "Breast cancer patients with upregulated CENPW presented with worse OS, DMFS, and DFS, which were similar to the results of the Kaplan-Meier plotter." (PMID 35783290, 2022). "We also evaluated the expression of CENPW with different clinicopathological features in breast carcinoma patients by the bc-GenExMiner online tool." (PMID 35783290, 2022). "The clinicopathological characteristics further suggest that CENPW expression is correlated with a worse prognosis of breast carcinoma." (PMID 35783290, 2022). "Growth curves suggested that CENPW knockdown suppressed the proliferation of these two breast carcinoma cell lines (*p < 0.05)." (PMID 35783290, 2022). "To reconfirm the function of CENPW in breast carcinoma prognosis, we illustrated the effect of CENPW on OS, DMFS, and DFS by bc-GenExMiner database." (PMID 35783290, 2022). "To better explore the potential value of CENPW in breast carcinoma patients, we further explored the expression and function of CENPW in breast carcinoma through several means." (PMID 35783290, 2022). "According to the outcome of the GEPIA database survival analysis, CDCA7 upregulation was correlated with poorer OS in breast carcinoma patients, which was consistent with the effect of CENPW on breast cancer." (PMID 35783290, 2022).
breast carcinoma (continued). "We further found that CENPW mainly influences the cell cycle pathway, and the downregulation of CENPW expression could inhibit the migration and proliferation of breast cancer cells and promote apoptosis." (PMID 35783290, 2022). "In summary, these results provide extensive data and experimental evidence that CENPW can serve as a novel predictor of breast cancer and may act as a prospective therapeutic target." (PMID 35783290, 2022). "We further explored the relationship between CENPW expression and breast carcinoma prognosis." (PMID 35783290, 2022). "Therefore, knockdown CENPW expression can suppress the proliferation and migration of breast cancer cells and induce apoptosis." (PMID 35783290, 2022). "This was consistent with the main biological effects of CENPW on breast cancer cells." (PMID 35783290, 2022). "Notably, we found that breast cancer cells with reduced CENPW expression were more sensitive to chemotherapeutic drugs that have been found to induce cell cycle arrest." (PMID 35783290, 2022). "Interestingly, we found that breast cancer cells with CENPW inhibited were more sensitive to chemotherapeutic drugs that have been found to induce cell cycle arrest." (PMID 35783290, 2022). "Notably, we believe that CENPW could be a biomarker in the development process of breast carcinoma and propose that inhibition of CENPW may be a prospective strategy for inhibiting breast carcinoma development." (PMID 35783290, 2022). "Next, we discovered that the genes interacting with CENPW are mainly concentrated in the cell cycle pathway, and CENPW is co-expressed with CDCA7, which is also highly expressed in breast carcinoma and leads to a worse prognosis." (PMID 35783290, 2022). "In addition, we analyzed the immune process of CDCA7 in the breast cancer microenvironment, and the expression level of CDCA7 was negatively correlated with macrophages, positively correlated with immune invasion of B cells, neutrophil, dendritic cell, which is consistent with the results of CENPW." (PMID 35783290, 2022).
gastric cancer (4 papers, 2020 to 2024). A primary or metastatic malignant neoplasm involving the stomach. "When the eight characteristic genes (ENTPD3, PDZD4, CNN1, GTPBP4, FPGS, UTP25, CENPW, and FAM111A) are all fitted into one variable, the AUC of the ROC curve is 0.996, indicating a good diagnostic efficiency for gastric cancer." (PMID 37007099, 2023). "We have established the early diagnosis model of eight characteristic genes (ENTPD3, PDZD4, CNN1, GTPBP4, FPGS, UTP25, CENPW, and FAM111A) for gastric cancer." (PMID 37007099, 2023). "Many previous studies have reported a high expression level of centromere protein E (CENP-E) and centromere protein W (CENP-W) in several solid tumors such as uterine cervical cancer, gastric cancer, and hypopharyngeal cancer." (PMID 33833984, 2021).
liver cancer (3 papers, 2018 to 2025). An epithelial or non-epithelial malignant neoplasm that arises from the liver. "CENPW gene is a highly expressed oncogene in liver cancer, and is related to the prognosis of HCC patients, being a potential diagnostic biomarker in HCC." (PMID 32635817, 2020). "In addition, the survival curves generated by the Kaplan-Meier plotter database showed that better prognosis of patients with liver cancer was correlated with lower CENPW expression." (PMID 32635817, 2020). "To investigate whether CENPW expression was correlated with prognosis in liver cancer patients, we used the Kaplan-Meier plotter database to evaluate the prognostic potential of CENPW based on the RNA sequencing data." (PMID 32635817, 2020). "We confirmed the overexpression of CENPW in liver cancer using the Oncomine database." (PMID 32635817, 2020). "We suggest that CENPW is a potential predictive biomarker for liver cancer prognosis." (PMID 32635817, 2020). "In summary, our study indicated that overexpression of CENPW implied unfavorable prognosis and CENPW might be the potential predictive biomarker in liver cancer." (PMID 32635817, 2020). "In this article, we found that CENPW was overexpressed in liver cancer tissues." (PMID 32635817, 2020). "However, the role of CENPW expression in the prognosis and development of liver cancer is still unknown." (PMID 32635817, 2020). "However, how CENPW expression affects biological processes in liver cancer cells remains unknown." (PMID 32635817, 2020). "Based on the results of single-cell pseudotime analysis, we examined the changes in the expression levels of the shared pathogenic genes (IGSF3, CENPW, CDC6, CDT1) from adjacent non-tumor cells to liver cancer cells during the continuous process." (PMID 40433415, 2025). "Notably, poor prognosis in liver cancer (OS HR = 1.95, 95% CI = 1.38 to 2.77, log-rank P = 0.00013; RFS HR = 1.89, 95% CI = 1.33 to 2.67, log-rank P = 0.00027) was correlated with high CENPW expression." (PMID 32635817, 2020). "Based on the analysis above, we hypothesized that CENP-W has biological functions other than its role as a centromeric component, and CENPW might be a potential predictive biomarker and a therapeutic target for liver cancer." (PMID 32635817, 2020).
hepatocellular carcinoma (2 papers, 2020 to 2024). A malignant tumor that arises from hepatocytes. "CENPW has been reported as a biomarker for hepatocellular carcinoma and a potential target for gene therapy in this cancer." (PMID 39062749, 2024).
leukemia (2 papers, 2020 to 2022). A malignant (clonal) hematologic disorder, involving hematopoietic stem cells and characterized by the presence of primitive or atypical myeloid or lymphoid cells in the bone marrow and the blood. "Considering all the cancers above, CENPW was downregulated only in leukemia." (PMID 32635817, 2020). "The data from the Oncomine database verified that the expression of CENPW was enhanced in numerous tumors including brain, breast, colorectal, head and neck, lung carcinomas compared with normal samples, while CENPW expression was lower in leukemia than in normal samples." (PMID 35783290, 2022).
type 1 diabetes (2 papers, 2021). "CENPW encodes centromere protein W, involved in kinetochore assembly and function, and associated with diseases such as type 1 diabetes." (PMID 33830993, 2021). "We did not replicate the findings that the associations near BCL11A, CENPW and THADA co-localise between the two diseases, despite overlapping samples and similar numbers of cases and controls in the type 1 diabetes GWAS." (PMID 33830302, 2021). "We did not replicate the finding that the chromosome regions near CENPW, GLIS3, BCL11A or THADA co-localised between type 1 and type 2 diabetes (H4PP CENPW=0.12, GLIS3=0.29, BCL11A=0.28, THADA not examined as no type 1 diabetes association existed in the region [FDR=0.07])." (PMID 33830302, 2021).
type 2 diabetes (2 papers, 2019 to 2021). "A recent analysis suggested that the same genetic variant alters risk of both type 1 and type 2 diabetes in five regions, near CENPW, CTRB1/BCAR1, GLIS3, BCL11A and THADA." (PMID 33830302, 2021).
acute myeloid leukemia (1 paper, 2022). Acute myeloid leukemia (AML) is a group of neoplasms arising from precursor cells committed to the myeloid cell-line differentiation. "On the contrary, the CENPW expression was lower than that of normal controls in acute myeloid leukemia." (PMID 35783290, 2022).
bladder cancer (1 paper, 2024). "Therefore, we suggest that knockdown of CENPW inhibits bladder cancer probably by repressing phosphorylation of STAT3." (PMID 38213721, 2024). "To further investigate the mechanism by which CENPW knockdown inhibits bladder cancer, we conducted a comparative analysis of the protein levels of STAT3 and P-STAT3 in both the si-NC group and si-CENPW group of 5637 and UM-UC-3 cells." (PMID 38213721, 2024). "To confirm the expression of CENPW in BLCA, we assessed both mRNA and protein expression levels in 14 pairs of samples include bladder cancer tissues and normal adjacent tissues." (PMID 38213721, 2024). "Additionally, the correlation between CENPW expression and CDK1, CCNB1, and PCNA was further investigated in 10 bladder cancer tissue samples." (PMID 38213721, 2024).
bladder urothelial carcinoma (1 paper, 2024). "Initially, the expression of CENPW was examined in normal urothelial cells SV-HUC-1 and bladder urothelial cancer cells (RT4, T24, J82, UM-UC-3, 5637)." (PMID 38213721, 2024).
breast tumor (1 paper, 2022). "In the study, we explored and revealed that abnormal CENPW expression is closely linked to breast tumors through various databases and in vitro cell experiments." (PMID 35783290, 2022).
ductal breast carcinoma (1 paper, 2022). "Similarly, we discovered that CENPW expression was up-regulated in ductal breast carcinoma and medullary breast carcinoma using two different online databases." (PMID 35783290, 2022).
male infertility (1 paper, 2016). The inability of the male to effect fertilization of an ovum after a specified period of unprotected intercourse. "Along these lines, retrotransposition of an almost full-length centromere protein W (CENPW) RNA, lacking 7 bp relative to the annotated TSS, into exon 8 of Poc1 centriolar protein A (Poc1a) resulted in growth insufficiency and male infertility in mouse (insertion size = 495 bp)." (PMID 27158268, 2016).
medullary breast carcinoma (1 paper, 2022). An infiltrating breast carcinoma with a relatively favorable prognosis. "In addition, the Curtis Breast dataset showed a 2.698-fold (p = 1.70E−09) increase in CENPW mRNA expression in medullary breast carcinoma." (PMID 35783290, 2022).
pancreatic acinar cell carcinoma (1 paper, 2025). An adenocarcinoma arising from the pancreas. "Additionally, a 77-year-old woman was diagnosed with pancreatic acinar cell carcinoma with an ROS1-Centromere Protein W (CENPW) gene." (PMID 41374970, 2025).
pituitary tumour (1 paper, 2018). "The genes associated with these terms included histones, pituitary tumour-transforming genes (PTTGs), a meiosis-specific kinetochore protein (MEIKIN) and Centromere Protein W (CENPW)." (PMID 29402920, 2018).
prostate carcinoma (1 paper, 2013). A carcinoma that arises from epithelial cells of the prostate gland. "For example: rs9388489 (T1D), rs1361108 (menarche, age at onset) and rs1490384 (height) near the CENPW gene; rs386000 (HDL) and rs103294 (prostate cancer) near the LILRA3 gene; and multiple trait associated SNPs at the SH2B3-ATXN2 locus were respectively in near perfect LD." (PMID 27896059, 2013).
triple-negative breast carcinoma (1 paper, 2022). An invasive breast carcinoma which is negative for expression of estrogen receptor (ER), progesterone receptor (PR), and human epidermal growth factor receptor 2 (HER2). "Simultaneously, CENPW was strongly elevated in triple-negative breast cancer (TNBC) patients." (PMID 35783290, 2022). "Additionally, the relation between CENPW expression and triple-negative breast carcinoma classification was analyzed, and the expression level of CENPW was the highest in TNBC-BL2." (PMID 35783290, 2022).
cancer (18 papers, 2011 to 2025). A tumor composed of atypical neoplastic, often pleomorphic cells that invade other tissues. "The data indicated that the CENPW expression was higher in female patients and was positively associated with patient age, nodal metastasis, and cancer stage." (PMID 35783290, 2022). "CENPW (centromere protein W), also known as cancer-upregulated gene 2 is suggested to have oncogenic activity as it is frequently upregulated in various cancer tissues and is known to play an important role in tumorigenesis." (PMID 38262937, 2024). "To clarify the molecular biological characteristics of CENPW in different tumors, we first investigated CENPW expression in cancers and adjoining normal tissues from various databases." (PMID 35783290, 2022). "CENPW was reported to be upregulated in many human cancer tissues, and exogenous CENPW overexpression was shown to induce tumorigenesis." (PMID 32635817, 2020). "In our study, we firstly confirmed the overexpression of the CENPW gene in various cancer tissues including HCC via analysis of the Oncomine database." (PMID 32635817, 2020). "Collectively, these results from different databases together revealed that CENPW is excessively upregulated in most tumors and may act as a potential indicator of cancer progression." (PMID 35783290, 2022). "Centromere protein W (CENP-W), which used to be called cancer-upregulated gene 2 (CUG2) protein, is overexpressed in various human cancers." (PMID 32635817, 2020). "By further confirmation using qRT-PCR, the transcription of the reprogramming factors (NANOG, OCT4, and SOX2) was enhanced by CENPW silencing in HCC cells, implying the possibility of reprogramming into cancer stem cells which characterized by inhibition of cell proliferation and metabolic changes." (PMID 32635817, 2020).
tumor (11 papers, 2013 to 2025). "Moreover, a high expression of CENPW is associated with tumor progression in BLCA and predicts a poorer DDS." (PMID 38213721, 2024). "In order to investigate the potential antitumor effects of CENPW knockdown in vivo, the tumor volume was measured every 3 days and a tumor growth curve was plotted." (PMID 38213721, 2024). "In comparison to adjacent normal tissues, tumor tissues exhibited significantly elevated levels of CENPW mRNA in 14 pairs of tissues (P < 0.001)." (PMID 38213721, 2024). "GEPIA database was further employed to evaluate the expression differences of CENPW in 33 kinds of tumor types." (PMID 35783290, 2022). "Locus BC046178 is associated with CENPW (previously known as C6orf173 or CUG2), a well-studied oncogene associated with apoptotic behaviours in tumour cells." (PMID 24037215, 2013). "Furthermore, we performed in vitro and in vivo experiments to assess the impact of CENPW knockdown on various tumor biological phenotypes in BLCA." (PMID 38213721, 2024). "Notably, CENPW principally affects the cell cycle process of tumor cells by regulating nucleosome assembly." (PMID 35783290, 2022). "Therefore, we hypothesized that CENPW might be involved in the mitosis of tumor cells." (PMID 38213721, 2024). "Centromeric protein W (CENPW), also known as cancer upregulated gene 2 (CUG2) protein, is overexpressed in multiple tumor tissues, including cervical, colon, liver, and lung cancers." (PMID 35783290, 2022). "The cell cycle (Cycling) program was characterized by high expression of genes involved in cell proliferation (e.g., CENPW, CKS1B, and BIRC5) and presented activation of the E2F targets, G2M checkpoint and MYC targets pathways, suggesting tumor cell proliferation." (PMID 34489433, 2021). "As anticipated, CENPW exhibited upregulation in BLCA tissues when compared to normal controls in TCGA (407 BLCA tissues versus 19 normal adjacent tissues, P < 0.001; 19 pairs of tumor tissues and normal adjacent tissues, P < 0.001)." (PMID 38213721, 2024).
CENPW also shares sentences with these, for which no sentence is quoted: lung carcinoma (4 papers); cervical cancer (2); colon cancer (2); esophageal cancer (2); ovarian carcinoma (2); pancreatic cancer (2); (CNS) cancer (1); cholangiocarcinoma (1); Cirrhosis (1); colorectal cancer (1); Dandy-Walker malformation (1); diabetes (1); Distichiasis (1); glioblastoma multiforme (1); head and neck cancer (1); head and neck squamous cell carcinoma (1); hypopharyngeal cancer (1); infection (1); microcephaly (1); neurodegenerative disease (1); neuroendocrine tumor (1); non-small cell lung carcinoma (1); oral squamous cell carcinoma (1); Pan (1); rectum cancer (1); stomach cancer (1); thyroid carcinoma (1).